LINC01121 (long independently transcribed non-coding RNA 1121)
Synonyms: UNQ6975
Gene: Long non-coding RNA gene on chromosome 2 (45,164,809 to 45,323,397, reverse strand). Ensembl gene ENSG00000205054.
Diseases named in the same sentence as LINC01121 in open-access papers:
LINC01121 is named in the same sentence as 5 diseases in open-access papers, as found by Europe PMC text mining. Sharing a sentence is not in itself a finding about the gene and the disease. The quoted sentences say what the papers report.
breast carcinoma (2 papers, 2023 to 2026). "Downregulation of LINC01121 in breast tumors is associated with the inhibition of cell proliferation, cell cycle progression, migration, and invasion in breast cancer cells." (PMID 36770654, 2023). "Previous research has indicated that the downregulation of LINC01121 significantly inhibits the development of breast cancer cells." (PMID 41488287, 2026). "The LINC01121 is substantially overexpressed in breast cancer cell lines compared with healthy breast epithelial cells." (PMID 36770654, 2023). "Furthermore, LINC01121 directly interacts with miR-150-5P, leading to the increase of HMGA2 level, which regulates metastasis in breast cancer." (PMID 41488287, 2026).
lymph node metastasis (1 paper, 2026). "Furthermore, when conducting stratified analyses, it was observed that in the samples classified as T2-4 group, lymph node metastasis group, and clinical stage III-IV group, patients exhibiting high levels of LINC01121 expression showed markedly poorer prognoses than those with lows LINC01121 level." (PMID 41488287, 2026).
prostate carcinoma (1 paper, 2026). A carcinoma that arises from epithelial cells of the prostate gland. "Moreover, LINC01121 is implicated in facilitating the metastasis of prostate cancer cells through the activation of the EMT process." (PMID 41488287, 2026).
tumor (2 papers, 2021 to 2022). "LINC01121, a newly identified tumor-related factor, was reported to be highly expressed in both BC specimens and the cell lines and exhibit a tumor-promotive role by promoting BC cell proliferation and invasion via regulating miRNA-150-5p/HMGA2." (PMID 39290802, 2021). "The results demonstrated that the expression of anti‐tumour lncRNAs DICER‐AS1, TUG1, GAS5 and LINC01121 was significantly increased by 50 μM resveratrol in combination with H19 knockdown, while expression of MALAT1 in cells was significantly downregulated by the combined treatment." (PMID 35166018, 2022).
LINC01121 also shares sentences with these, for which no sentence is quoted: colorectal cancer (1 paper).